IRF3 (interferon regulatory factor 3)
Diseases named in the same sentence as IRF3 in open-access papers (continued):
Sharing a sentence is not in itself a finding about the gene and the disease.
Obesity (32 papers, 2015 to 2026). Accumulation of substantial excess body fat. "Taken together, these results indicate that IRF3 deficiency in adipocytes is sufficient to attenuate obesity-induced insulin resistance at thermoneutrality." (PMID 38816388, 2024). "Our findings showed, for the first time, an impaired RIG-I/IRF3 axis in the decidua of the placenta from mothers with obesity in association with ZIKV infection." (PMID 36851534, 2023). "Taken together, we observed that pregestational obesity in association with ZIKV infection altered the RIG-I/IRF3 axis in the placenta." (PMID 36851534, 2023). "Further investigation into the mechanisms by which IRF3 regulates various cellular compartments in metabolism will help us to develop novel strategies to target IRF3 for the prevention and treatment of obesity-associated diseases." (PMID 34091599, 2021). "Bone-marrow reconstitution experiments further demonstrated that both nonhematopoietic and hematopoietic cells contributed to the development of obesity-associated metabolic abnormalities in IRF3 KO mice." (PMID 34091599, 2021). "Together, these results demonstrate that IRF3 restrains obesity-associated macrophage inflammatory activation through IFNβ-induced IL-10." (PMID 34091599, 2021). "There findings support a protective role of IRF3 in the development of obesity-associated metabolic abnormalities." (PMID 34091599, 2021). "Here, we show that IRF3 is critical for controlling this process by acting as a brake to prevent hypertrophic obesity, an underlying pathological alteration linked to the development of obesity-associated diseases including IR and T2D." (PMID 34091599, 2021). "IRF3 regulates the development of obesity and obesity-associated diseases through multiple mechanisms." (PMID 34091599, 2021). "The IRF3 KO mice develop obesity, IR and T2D spontaneously associated with the development of WAT inflammation." (PMID 34091599, 2021). "For PPP2R1B elevation, a recent study has demonstrated that the upregulation of the PPP2R1B gene, directly targeted by the transcription factor IRF3, is associated with increased dysglycemia and impaired glucose regulation in patients with obesity and non-alcoholic fatty liver disease." (PMID 40711007, 2025). "In the cytosol, IRF3 was shown to bind to inhibitor of kappa B kinase beta (IKKβ) and represses IKKβ/NF‐κB signaling, uncovering a non‐canonical role of cytosolic IRF3 in preventing NF‐κB‐mediated inflammation during obesity." (PMID 39158380, 2025). "We, therefore, identify the adipocyte IRF3/AIG1 axis as a crucial link between obesity-induced inflammation and insulin resistance and suggest an approach for limiting the metabolic dysfunction accompanying obesity." (PMID 38816388, 2024). "We have provided evidence that the pro-inflammatory transcription factor IRF3 is a critical driver of insulin resistance in the context of obesity." (PMID 38816388, 2024). "We have also shown that IRF3 becomes activated in the hepatocytes and adipocytes of people and mice with obesity, where it mediates cellular and systemic insulin resistance." (PMID 38816388, 2024). "We also verified a decreased expression of IRF-3 in the placental decidua of mothers with obesity (area p = 0.0015; ODI p = 0.0015; area/basement membrane p = 0.0004)." (PMID 36851534, 2023). "In children, the adipose tissue level of IRF7 mRNA was strongly increased by overweight and obesity (body mass index standard deviation score over 1.28), while the level of IRF3 mRNA was unrelated to obesity status." (PMID 36443525, 2022). "In conclusion, our data show that the AT SRA1 expression correlates with TLRs-3,4,7,9, MyD88, NF-κB, and IRF5 expression in individuals with T2D and with TLR2, IRAK1, and IRF3 expression in individuals with obesity." (PMID 36552771, 2022). "This suggests that obesity-associated Fabp1 upregulation is promoted by fatty acids via the PPARα and TBK1–IKKε–IRF3 pathways." (PMID 36400935, 2022).
Obesity (continued). "The novel regulator of macrophage polarization Kruppel-like factor 4 (KLF4) also controls adipogenesis, while IRF3 plays an important role in the regulation of insulin sensitivity, inflammation, and obesity." (PMID 35456006, 2022). "The interferon regulatory factor 3 (IRF3) plays an important role in obesity and the regulation of insulin sensitivity." (PMID 35456006, 2022). "To investigate the contribution of nonhematopoietic cells such as adipocytes to the development of obesity and T2D in IRF3 KO mice, we lethally irradiated WT and IRF3 KO mice followed by transferring WT bone-marrow (WT-BM) cells." (PMID 34091599, 2021). "To investigate the contribution of hematopoietic cells such as macrophages to the development of obesity and T2D in IRF3 KO mice, we transferred WT- or KO-BM cells to lethally irradiated WT mice." (PMID 34091599, 2021). "Together, these results demonstrate that the development of obesity in IRF3 KO mice is accompanied by increased M1 macrophage infiltration and WAT inflammation, which contributed to impaired insulin sensitivity." (PMID 34091599, 2021). "IRF3 KO mice have less energy expenditure and reduced activity compared to WT mice, which result in a positive energy balance and subsequent obesity." (PMID 34091599, 2021). "The function of IRF3 in multiple cellular compartments work cooperatively to prevent the development of obesity-related metabolic abnormalities including IR and T2D." (PMID 34091599, 2021). "The IRF3 knockout (KO) mice develop obesity, insulin resistance, glucose intolerance, and eventually type 2 diabetes with aging, which is associated with the development of white adipose tissue (WAT) inflammation." (PMID 34091599, 2021). "However, the role of IRF3 in obesity and obesity-associated disorders remains unclear." (PMID 34091599, 2021). "To examine the role of IRF3 in obesity, we compared the body weight of gender- and age-matched WT and IRF3 KO mice at various ages." (PMID 34091599, 2021). "On the molecular level, IKKε (IκB kinase ε) and IRF3 (interferon regulatory factor-3) are among the main inflammation regulators in obesity." (PMID 32265845, 2020). "Next, we also found that individuals with obesity have high levels of phospho-IRF3 in THP-1 monocytes compared to lean." (PMID 33050324, 2020). "Our data show strong positive correlations between adipose IRF5 gene expression and that of TLR2, TLR7, TLR8, TLR9, MyD88, IRAK-1, and IRF3 in obesity." (PMID 31718015, 2019). "Furthermore, Irf3−/− mice develop obesity, insulin resistance, glucose intolerance, and eventually T2D with aging, which is associated with increased inflammatory responses and adipogenesis." (PMID 39158380, 2025). "Furthermore, pharmacological inhibition of AIG1 reversed obesity-induced insulin resistance and restored glucose homeostasis in the setting of adipocyte IRF3 overexpression." (PMID 38816388, 2024). "Variation at the IRF3 locus has not been associated with body weight in humans, either in GWAS studies or in exome sequencing of patients with extreme obesity." (PMID 38821928, 2024). "The downregulation of the RIG and IRF-3 was not related to the placentas of the mothers that had newborns with microcephaly, whereas it was related to the obesity associated with ZIKV infection." (PMID 36851534, 2023). "SRA1 expression associated with TLR2, IRAK1, and IRF3 expression only in individuals with obesity, regardless of diabetes status." (PMID 36552771, 2022). "In the current study, we examined whether the human adipose tissue SRA1 expression associated with TLRs expression, their adaptor proteins and TLR-downstream signaling molecules including NF-κB, IRF3, 4, and 5 in obesity and/or T2D." (PMID 36552771, 2022). "Therefore, IFNβ-induced IL-10 is a major mechanism by which IRF3 inhibits macrophage inflammatory activation and adipose tissue inflammation in obesity." (PMID 34091599, 2021).
Obesity (continued). "Overexpression of IRF3 in the adipocytes in both human and mouse obesity has been reported." (PMID 33050324, 2020). "We found that individuals with obesity have a high expression of p-IRF3 compared to lean individuals, suggesting that plasma free fatty acids in individuals with obesity contribute to the activation of proinflammatory genes regulated under the influence of IRF3." (PMID 33050324, 2020). "Individuals with obesity show high IRF3 expression in monocytes as compared to lean individuals." (PMID 33050324, 2020). "In contrast, the role of IRF3 in obesity is more controversial." (PMID 33574823, 2020). "Animal studies demonstrated that HFD-induced obesity could induce low-grade systemic inflammation through activating nuclear factor (NF)-κB pathway and interferon regulatory factor (IRF)-3 signaling." (PMID 31664141, 2019). "Furthermore, IRF3 also controls the development of WAT inflammation in obesity." (PMID 34091599, 2021). "Increased expression of IRF3 has also observed in adipocytes from HFD-fed obese mice and in humans with obesity." (PMID 38164186, 2024). "IRF3 and IRF7 are key transcription factors regulating ISGs; however, their role in obesity development is conflicting." (PMID 36443525, 2022). "Consistent with our finding of the increased expression of these markers, at least in part, similar changes in the adipose tissue expression of MyD88, IRF3, NF-κB, and AML1 have been reported in obesity and/or T2D." (PMID 32188105, 2020). "Both IRF3 and IRF7 are involved in the induction of IFN-I production, which has also been reported to play an important role in obesity-mediated metabolic syndromes." (PMID 33574823, 2020). "During obesity, dietary saturated fatty acids lead to the activation of TLR2 and TLR4 in ATMs, which is followed by the activation of interferon regulatory factor-3 (IRF3), JNK, and NF-κB and subsequent inflammatory signaling." (PMID 26136779, 2015). "Notably, DPR also inhibited palmitate‐induced IRF3 activation and IFN‐γ expression, supporting the notion that DPR attenuates obesity‐induced cardiac inflammaging through the AMPK‐ULK1‐dependent pathway." (PMID 41549510, 2026). "IRF3 levels are increased in the adipocytes of people and mice with obesity, and mice lacking IRF3 in all tissues show improved insulin sensitivity before body weight divergence after high fat feeding." (PMID 38816388, 2024). "The maternal placental side, decidua, and the fetal side, villus, from ZIKV-infected mothers with and without obesity were analyzed by immunohistochemistry for IRF-3, RIG-I, and IFN-α." (PMID 36851534, 2023). "It should be noted that ZIKV infection in association with obesity, induced a decrease in the transcriptional RIG-I, IFIH1, and IRF3 expression in the placental tissue, compared to the non-obese group." (PMID 36851534, 2023). "Finally, motif analysis revealed that promoter regions open in monocytes from lean subjects at T3 (closed in monocytes from subjects with obesity) harbor binding sites for transcription factors PU.1 and AP-1 and interferon regulators IRF1, IRF3, and IRF8." (PMID 34195568, 2021). "In this study, with an obesity-related DCM mouse model established by feeding db/db mice with a high-fat diet (HFD), we observed increased mtDNA in the cytosol and activated cGAS-STING signaling pathway during DCM, as well as the downstream targets, IRF3, NF-κB, IL-18, and IL-1β." (PMID 35235096, 2023). "Moreover, signaling via TLR4 induces nuclear factor, such as IRF3 and NF-κB, translocation, leading to the production of cytokines, the activation of the cyclooxygenase-2 (COX2) pathway, and consequently, chronic inflammation in people with obesity." (PMID 36851534, 2023). "Taken together, these data suggest that HFD induces the IRF3, TGFβ1, and STAT3 signaling pathways in AT that in part might suppress the expression of PPAR-γ to maintain low-grade chronic inflammation in AT during HFD-induced obesity." (PMID 35456006, 2022).
Obesity (continued). "Therefore, the nonhematopoietic compartment in IRF3 KO mice is primary responsible for the development of obesity, whereas both the nonhematopoietic and hematopoietic compartments contribute to the development of the impaired glucose tolerance." (PMID 34091599, 2021). "Bone-marrow reconstitution experiments demonstrate that the nonhematopoietic cells are the primary contributors to the development of obesity and both hematopoietic and nonhematopoietic cells contribute to the development of obesity-related complications in IRF3 KO mice." (PMID 34091599, 2021). "Therefore, IRF3-mediated IFN-I production may have tissue-specific functions and play a protective role in liver pathology induced by obesity." (PMID 33574823, 2020). "When assessing the placental expression of factors related to viral recognition (TLR3, TLR7, and IRF3) and antiviral response (IFNs I and III, STING, RIG-I, MxA, and ISG15) from parturient with pregestational obesity (BMI ≥ 25), no changes were detected between the obese and non-obese samples." (PMID 36851534, 2023).
melanoma (31 papers, 2013 to 2026). A malignant, usually aggressive tumor composed of atypical, neoplastic melanocytes. "Given the importance of immunotherapy in melanoma, the modulation of IRF3 function by these mutations and its downstream immune effects merits further exploration." (PMID 40359938, 2025). "By annotating to expressed transcripts, we identify a number of overlooked functional non-coding mutations in melanoma, including IRF3/BCL2L12 promoter mutations." (PMID 40359938, 2025). "UV exposure significantly reduced the susceptibility of melanoma cells to CD8+ T cell-dependent cytotoxicity through activation of the HMGB1/TBK1/IRF3/NF-κB cascade which in turn triggers the PD-1/PD-L1 checkpoint." (PMID 36012593, 2022). "Interestingly, IRF3 and BCL2L12 mRNA expression was significantly reduced in melanoma tumors with an IRF3/BCL2L12 promoter mutation as compared to tumors with a wild-type promoter region." (PMID 40359938, 2025). "In keeping with these findings, newly we showed that, upon doxorubicin treatment, TG2 translocates into the nucleus and catalyzes the formation of covalent cross-linked IRF3 (Interferon regulatory factor 3) dimers, thereby limiting the production of IFNβ in dying melanoma cells." (PMID 36695883, 2023). "Co-immunoprecipitation experiments showed that Poly(I:C)-induced dimerization of IRF7 and IRF3 was reduced in NOS1 overexpressing melanoma cells." (PMID 41535256, 2026). "Together with the first hotspot, these mutations have a combined frequency of 3.8%–5.5% and result in downregulation of BCL2L12 and IRF3 expression in melanoma tumors." (PMID 40359938, 2025). "To assess the functionality of the identified IRF3/BCL2L12 promoter mutations, we evaluated their impact on IRF3 and BCL2L12 mRNA expression in melanoma tumor samples." (PMID 40359938, 2025). "As previously reported, IFN‐β treatment significantly inhibited the proliferation of the B16‐F10 melanoma cells, whereas knockout of cGAS and IRF3 reversed the inhibitory effects of IFN‐β." (PMID 39004913, 2024). "We demonstrated the efficacy of LiSmore in vivo by showing light-triggered TBK1 and IRF3 phosphorylation in LiSmore-engineered bone marrow-derived dendritic cells (BMDCs) within the tumor-draining lymph nodes (tdLNs) of B16 melanoma-bearing mice." (PMID 37673917, 2023). "Type 1 interferon has been reported to enhance apoptosis in melanoma cells and is dependent on the phosphorylation and dimerization of the transcription factor IRF3." (PMID 35044632, 2022). "Since the IFN-γ signaling pathway in melanoma cells induces tumor growth arrest and death, mutations of IFNGR1, IFNGR2, JAK1, JAK2, STAT1, and IRF3 lead to insensitivity to anti-tumor IFN-γ activity." (PMID 35432377, 2022). "De novo HLA-I APM expression is IRF1/IRF3-dependent and re-sensitizes melanoma cells to autologous cytotoxic CD8+ T cells." (PMID 33554047, 2021). "Concurrently, we show that STING is phosphorylated which subsequently leads to the phosphorylation of TBK1 and IRF3 in melanoma cells when treated with diABZI." (PMID 32477956, 2020). "Ectopic expression of IRF-3 decreased melanoma and cervical cancer cells growth rate in vivo and in vitro, while suppressed IRF-3 block B-lymphoid cell differentiation in acute lymphoblastic leukemia." (PMID 29100282, 2017). "data in melanoma cells 34.Further investigations are needed to better understand the molecular mechanism of IRF-3-mediated apoptosis in PCa cells." (PMID 25444175, 2015). "Next, the three IRF3/BCL2L12 promoter mutations that we had identified in melanoma were each introduced heterozygously and without additional mutations into Mel-ST cells using CRISPR-Cas9." (PMID 40359938, 2025).